C6orf120 (chromosome 6 open reading frame 120)
Description:
May be involved in induction of apoptosis in CD4(+) T-cells, but not CD8(+) T-cells or hepatocytes.
Synonyms: bA160E12.4
Tractability: Antibody: UniProt places it where antibodies can reach, with high confidence; its Gene Ontology location is reachable by antibodies, with high confidence; UniProt predicts a signal peptide or a membrane-spanning region. PROTAC: ubiquitination databases record sites on it; its protein half-life has been measured.
Gene: Protein-coding gene on chromosome 6 (169,702,126 to 169,706,360, forward strand). Ensembl gene ENSG00000185127.
Subcellular location: Secreted
Pathways (Reactome):
Immune System: Neutrophil degranulation
Gene Ontology:
Molecular function: protein binding
Cellular component: azurophil granule lumen; extracellular region
Genetic constraint (gnomAD): Loss-of-function variants: 0 observed, 1.55 expected, observed/expected ratio (o/e) 0, 90% interval 0 to 1.53. That is too few expected variants to judge how well the gene tolerates losing a copy. Missense variants: 311 observed, 279.89 expected, observed/expected ratio (o/e) 1.11, 90% interval 1.01 to 1.22. Synonymous variants: 165 observed, 129.42 expected, observed/expected ratio (o/e) 1.27, 90% interval 1.12 to 1.45.
Homologues: Orthologues: chimpanzee C6H6orf120 (98% identical), macaque C4H6orf120 (98% identical), rabbit C6orf120 (79% identical), pig C6orf120 (77% identical), mouse 1600012H06Rik (73% identical), rat C1h6orf120 (73% identical), guinea pig C6orf120 (69% identical), tropical clawed frog c5h6orf120 (58% identical), zebrafish C11H6orf120 (56% identical).
Diseases named in the same sentence as C6orf120 in open-access papers:
C6orf120 is named in the same sentence as 7 diseases in open-access papers, as found by Europe PMC text mining. Sharing a sentence is not in itself a finding about the gene and the disease. The quoted sentences say what the papers report.
liver cancer (1 paper, 2017). An epithelial or non-epithelial malignant neoplasm that arises from the liver. "A previous study demonstrated that C6orf120 is secreted from HepG2 liver cancer cells via the classical ER-Golgi secretory pathway." (PMID 28002789, 2017).
tumor (2 papers, 2017 to 2025). "To further clarify the role of C6orf120 in tumor immunity, we analyzed its association with seven key immune cell types (B cells, CD8+ T cells, CD4+ T cells, M1 macrophages, M2 macrophages, neutrophils, and dendritic cells) in LIHC using the GEPIA database." (PMID 39388711, 2025). "Given the crucial role of immunity in tumor initiation and progression, evaluating the interaction between C6orf120 and immune processes is essential." (PMID 39388711, 2025). "Our study suggests that C6orf120 influences not only the immune landscape of LIHC but also the regulation of tumor angiogenesis, indicating that C6orf120 could be a strategic target for an integrated approach to cancer therapy that encompasses both targeted therapy and immunotherapy." (PMID 39388711, 2025). "To provide a comprehensive view of C6orf120 in the immune landscape of LIHC, we analyzed its correlation with tumor-infiltrating lymphocytes, co-stimulatory molecules, and co-inhibitory markers across various cancers using the TISIDB database." (PMID 39388711, 2025). "The expression of C6orf120 and PRKACB was assessed by qPCR in pre-treatment tumor biopsies from EAC patients (n=30), who subsequently received neoadjuvant CRT." (PMID 28002789, 2017). "IHC revealed significantly higher C6ORF120 protein expression in tumor samples compared to adjacent normal tissues." (PMID 39388711, 2025). "Given that miR-17-5p expression is significantly lower in pre-treatment tumor biopsies from EAC patients who subsequently have a poor response to neoadjuvant CRT, we hypothesised that C6orf120 and PRKACB would consequently be upregulated in poor responder tumors." (PMID 28002789, 2017).
cancer (1 paper, 2025). A tumor composed of atypical neoplastic, often pleomorphic cells that invade other tissues. "At the protein level, data from the HPA database indicated markedly elevated C6ORF120 protein expression in cancer tissues." (PMID 39388711, 2025). "C6orf120’s prognostic relevance was assessed across various cancer types, with notable findings in LIHC." (PMID 39388711, 2025). "Pan-cancer analyses and Kaplan–Meier survival curves from the TCGA database identified C6orf120 expression as a predictive factor for OS and five-year survival rates." (PMID 39388711, 2025). "Therefore, investigating the interaction mechanisms between C6orf120 and these molecules could yield valuable insights into the construction of a novel cancer regulatory network." (PMID 39388711, 2025).
liver (1 paper, 2025). "The C6orf120 gene exhibited significant expression in the liver and was correlated with an array of liver pathologies." (PMID 39388711, 2025).
C6orf120 also shares sentences with these, for which no sentence is quoted: esophageal carcinoma (1 paper); head and neck squamous cell carcinoma (1); lung squamous cell carcinoma (1).